NAPSA (napsin A aspartic peptidase)
Description:
May be involved in processing of pneumocyte surfactant precursors.
Synonyms: NAP1; NAPA; Kdap; KAP; NR1H2-AS1; SNAPA
Tractability: Small molecule: it belongs to a druggable protein family. Antibody: UniProt places it where antibodies can reach, with high confidence; UniProt predicts a signal peptide or a membrane-spanning region; its Gene Ontology location is reachable by antibodies, with medium confidence.
Gene: Protein-coding gene on chromosome 19 (50,358,472 to 50,365,830, reverse strand). Ensembl gene ENSG00000131400.
Subcellular location: Secreted
Pathways (Reactome):
Metabolism of proteins: Surfactant metabolism
Gene Ontology:
Molecular function: endopeptidase activity; peptidase activity; protein binding; aspartic-type endopeptidase activity
Biological process: membrane protein proteolysis; surfactant homeostasis; proteolysis
Cellular component: alveolar lamellar body; extracellular exosome; extracellular region; lysosome; multivesicular body lumen
Genetic constraint (gnomAD): Loss-of-function variants: 38 observed, 38.16 expected, observed/expected ratio (o/e) 1, 90% interval 0.77 to 1.3. The upper end of that interval is the gene's LOEUF score, 1.3, which puts it in group 5 of 6, group 1 being the genes least tolerant of losing a copy. Missense variants: 532 observed, 567.26 expected, observed/expected ratio (o/e) 0.94, 90% interval 0.87 to 1.01. Synonymous variants: 222 observed, 245.76 expected, observed/expected ratio (o/e) 0.9, 90% interval 0.81 to 1.01.
Homologues: Orthologues: chimpanzee NAPSA (99% identical), macaque NAPSA (94% identical), pig NAPSA (80% identical), guinea pig NAPSA (75% identical), dog NAPSA (71% identical), mouse Napsa (71% identical), rat Napsa (70% identical), tropical clawed frog napsa (49% identical), zebrafish napsa (47% identical), Drosophila melanogaster CG17134 (39% identical), Drosophila melanogaster CG33128 (37% identical), Drosophila melanogaster Bace (36% identical), and 11 more. Paralogues in human: CTSD (45% identical), CTSE (41% identical), REN (39% identical), PGA5 (38% identical), PGA3 (38% identical), PGA4 (38% identical), PGC (35% identical), BACE2 (26% identical), BACE1 (24% identical).
Diseases named in the same sentence as NAPSA in open-access papers:
NAPSA is named in the same sentence as 120 diseases in open-access papers, as found by Europe PMC text mining. Sharing a sentence is not in itself a finding about the gene and the disease. The quoted sentences say what the papers report.
lung adenocarcinoma (110 papers, 2003 to 2026). A carcinoma that arises from the lung and is characterized by the presence of malignant glandular epithelial cells. "Another helpful antibody—particularly in the diagnosis of adenocarcinomas of the lungs—is Napsin A. Napsin A is an enzyme that can be assigned to the aspartate proteases, and t is encoded in the NAPSA gene located on chromosome 19 in section q13.3." (PMID 40564811, 2025). "Expression of oncogenes including phospho-Src, phospho-β-catenin, c-myc, and cyclin D1 were also detected in the tumor-like tissues, as were diagnostic markers for lung adenocarcinoma, such as TTF1, NAPSA, CK7, and CK-HMW." (PMID 26871601, 2016). "Therefore, NAPSA may be an effective therapeutic target for lung adenocarcinoma." (PMID 36311724, 2022). "Additionally, anti-beta-arrestin-1 stained positive for all 6 metastatic lung adenocarcinoma in specimens from their metastatic sites, whereas anti-TTF1 and anti-NAPSA unambiguously stained only 2 (from patients 19 and 29) and 3 samples (from patients 22, 19 and 34), respectively." (PMID 30078843, 2018).
lung carcinoma (40 papers, 2011 to 2026). "A slightly less specific marker is Napsin A, which is a protein encoded by the NAPSA gene and is useful for distinguishing adenocarcinoma from other lung cancers." (PMID 37444584, 2023). "NAPSA is a pronapsin gene, which may have a considerable diagnostic value as a marker for primary lung cancer." (PMID 29236770, 2017). "Hence, this specific cluster and its distinct gene expression markers (GPRC5A, NAPSA, and SLC34A2) hold promise as prognostic indicators for lung cancer, a prominent source of brain metastases." (PMID 39058687, 2024).
ovarian carcinoma (7 papers, 2016 to 2025). A malignant neoplasm originating from the surface ovarian epithelium. "Literature review found Cofilin 1 (CFL1), Ezrin (EZR), Cyclophilin-A (CYPA), Profilin 1 (PFN1), Napsin A (NAPSA) have been found to be associated with the development and progression of OC15–19, and are potential TAAs for ovarian cancer." (PMID 38684875, 2024).
ovarian clear cell cancer (5 papers, 2013 to 2024). An invasive malignant neoplasm that arises from the ovary and is characterized by a predominance of clear and hobnail malignant epithelial cells. "Most of the samples included in this study were serous type OC, and only 8 cases of ovarian clear cell carcinoma (OCCC) were known, and NAPSA was often abnormally high expressed in OCCC, which may be the reason for the insignificant difference in anti-TAA autoantibodies." (PMID 38684875, 2024).
Pleural effusion (4 papers, 2012 to 2026). The presence of an excessive amount of fluid in the pleural cavity. "We also identified pleural effusion predictive gene signatures, including TMPRSS3, MS4A7, NAPSA, and IGFBP2, while liver metastasis predictive markers included WFDC2, HSPB1, COX6C, APOE, and TUBA1A." (PMID 39955556, 2025).
COVID-19 (3 papers, 2020 to 2023). A disease caused by infection with severe acute respiratory syndrome coronavirus 2. "Surprisingly, NAPSA was dysregulated in the COVID-19-affected lung." (PMID 33173052, 2020).
kidney cancer (2 papers, 2021 to 2022). Primary or metastatic malignant neoplasm involving the kidney. "The NAPSA gene is highly expressed mainly in LUAD and kidney cancer; therefore, the NAPSA gene may be closely related to tissue typing." (PMID 36311724, 2022).
glioma (1 paper, 2020). A benign or malignant brain and spinal cord tumor that arises from glial cells (astrocytes, oligodendrocytes, ependymal cells). "Interestingly, seven urinary proteins were differentially abundant between glioma and meningioma patients, including AMP4, CD276, LAMP1, NAPSA, LEG1, DNAS1, and BGAL." (PMID 32922940, 2020).
tumor (100 papers, 2011 to 2026). "WFDC2, along with NAPSA and MUC1, was upregulated in PD-L1–positive tumor cells, suggesting its potential role in immune evasion." (PMID 40723266, 2025). "Among the genes with significant differences, NAPSA, MUC1, WFDC2, and MYO6 were well correlated with Tumor_C1 and Unknow_C2 (cells with a high positive rate of tumor markers), and these two cell clusters were all cells with a high positive rate of PD-L1." (PMID 39991571, 2025). "While TTF1, CK7, and NAPSA are routinely utilized for tumor origin identification and classification, LPL offers a novel perspective by reflecting changes in tumor metabolism and the tumor microenvironment." (PMID 40427755, 2025). "Among 6 epithelial clusters identified in these tumor samples, cluster 2′ showed increased expression of squamous markers, and decreased expression of adenomatous markers such as NKX2.1 and NAPSA, and this cluster became dominant at the PD stage." (PMID 39687207, 2024). "We selected four markers that were differentially expressed in normal and tumor human lung tissues: CADM1, KRT16, MMP1, and NAPSA." (PMID 38067281, 2023). "Interestingly, the results observed that 5 hub genes were shared in the GEO and TCGA profiles, including SLC44A3, DBF4, NAPSA, ATP6V0A4, and CLDN4, which were closely associated with B cells, CD4+ T cells, CD8+ T cells, Macrophage, Neutrophil, and Dendritic cells to involve in tumor immunity." (PMID 36325324, 2022). "Conversely, the underexpression of genes like PEBP1, NAPSA, and FDX1 in ccRCC may indicate their roles as tumor suppressors or regulators of critical cellular processes." (PMID 37985807, 2023). "For example, specimen P7 is a LUSC tumor with strong TP63/CK expressions and weak NAPSA expression." (PMID 33953163, 2021). "Napsin (NAPSA) was expressed in only one of the 2 AC, while TTF1 (NKX2-1) was strongly expressed in one AC, and expressed at lower levels in one ASC line, neither of these tumor markers was present in the stroma." (PMID 24324581, 2013).
adenocarcinoma (99 papers, 2012 to 2026). A common cancer characterized by the presence of malignant glandular cells. "To understand these signatures in more detail, we explored the expression of canonical markers of adenocarcinoma and squamous differentiation, namely NAPSA (which encodes Napsin A) and TP63 (which encodes both p63 and p40), respectively." (PMID 37024582, 2023). "They observed pervasive transcriptional downregulation of adenocarcinoma lineage markers (NAPSA, NKX2-1, SFTA2, and SFTA3), validated orthogonally via multiplex immunohistochemistry." (PMID 41516316, 2025). "The staining of thyroid transcription factor 1 (TTF-1/NKX2–1) or napsin-A (NAPSA) can be used to support the diagnosis when the morphological feature of adenocarcinoma is unclear." (PMID 34187403, 2021). "Parallel to that, 5 proteins were expressed lower in SOL adenocarcinomas and the low expression of which was correlated with poor OS, including PIGR, CHDH, NAPSA, PLEKHA7 and SELENBP1." (PMID 38182978, 2024).
cancer (38 papers, 2011 to 2025). A tumor composed of atypical neoplastic, often pleomorphic cells that invade other tissues. "We were particularly interested in studying those genes that are associated with cancer progression, TME signals, and poor prognosis such as LY6E, NAPSA, MUC1, ELF3, and FOS." (PMID 33144684, 2021). "Furthermore, it is interesting to note that upregulation of genes, such as ANKRD22, FRMD6, and KIR3DL2, and down-regulation of genes, such as TIMP3, SAP25, NAPSA, and TIMP are associated with a worse prognosis in cancer, are also associated with a worse prognosis in AdHF." (PMID 29236770, 2017). "Subsequently, the LUAD marker genes NAPSA, NKX2-1, the LUSC marker genes TP63, KRT5, as well as EPCAM and MET were adopted to identify the cancer cell clusters." (PMID 38382091, 2024). "Cancer cells were identified with canonical markers of LUAD and alveolar epithelial cells (e.g., SFTPB, SFTPC, EPCAM, NAPSA, and NKX2-1)." (PMID 35874770, 2022). "We found that the cancer subtype markers (GRP, CHGB, NEUROD1, and CHGA for NET; KRT5, DSC3, KRT6B, TP63, and KRT6A for SCC; and NKX2-1, KRT7, NAPSA, and MUC1 for ADC) were specifically expressed in the corresponding cancer subtypes." (PMID 35962452, 2022).
lung (3 papers, 2017 to 2020). "Napsin‐A (NAPSA) and anterior gradient protein 2 homolog (AGR2) were identified as potential stage‐specific candidates for stage IA and stage IIIA lung ADC." (PMID 32536039, 2020).
NAPSA also shares sentences with these, for which no sentence is quoted: squamous cell carcinoma (30 papers); clear cell carcinoma (29); thyroid cancer (11); non-small cell lung carcinoma (8); renal cell carcinoma (8); breast carcinoma (7); lung squamous cell carcinoma (7); serous carcinoma (7); endometrioid carcinoma (5); infection (5); metastatic tumors (5); papillary thyroid carcinomas (5); small cell carcinoma (5); colorectal cancer (4); melanoma (4); mucinous adenocarcinoma (4); neuroendocrine tumors (4); bladder adenocarcinoma (3); endometrial carcinoma (3); gastric adenocarcinoma (3); gastrointestinal tumors (3); lymph node metastasis (3); malignant mesothelioma (3); mesothelioma (3); adenocarcinomas of the prostate (2); adenoma (2); clear cell adenocarcinoma of the ovary (2); colon adenocarcinoma (2); colon cancer (2); colorectal adenocarcinoma (2).
A further 78 diseases each share a sentence with NAPSA in 2 papers or fewer.